PROX1 (prospero homeobox 1)
Diseases named in the same sentence as PROX1 in open-access papers (continued):
Sharing a sentence is not in itself a finding about the gene and the disease.
thyroid cancer (continued). "However, in all tested thyroid cancer cell lines and tissues of different origins, we observed the inverse PROX1:FGF2 relation." (PMID 31717665, 2019). "A decrease in PROX1 expression was recently observed in thyroid cancer when compared to adjacent healthy tissue, and reintroduction of PROX1 in papillary thyroid cancer (PTC) cell lines abolished the malignant properties (growth, adhesion and invasiveness) of these cells." (PMID 29934628, 2018). "Moreover, induced PROX1 gene reactivation in advanced stages of thyroid cancer might represent a novel therapeutic strategy in terms of the inhibition of disease progression." (PMID 35885529, 2022). "Additionally, in vitro and animal experiments indicate that the downregulation and inactivation of PROX1 might play a significant role in thyroid cancer initiation and development." (PMID 35885529, 2022). "Many studies have described a significant impact of PROX1 on the biology of different cancer types, including tumours of the central nervous system and the liver, oesophageal squamous cancer, colon cancer, haematological malignancies as well as breast, pancreatic and thyroid cancers." (PMID 31060342, 2019). "In addition, PROX1 inactivation seen in PTCs promotes the malignant behaviour of thyroid carcinoma and suggest that PROX1 reactivation could be considered as potential therapeutic factor." (PMID 31060342, 2019). "Therefore, to investigate if reciprocal levels of PROX1 and MMP14 would be observed also in thyroid cancer, we performed double-staining IHC for PROX1 and MMP14 on a tissue microarray (TMA) including 57 specimens of which 44 originated from different thyroid cancers and 13 from benign hyperplasias." (PMID 29934628, 2018). "In thyroid cancer cell lines (FTC-133 and CGTH-W-1), PROX1 and VEGFC are expressed, and in CGTH-W-1 cells, VEGFC was oppositely regulated by PROX-1 knockdown, which enhanced the VEGFC expression level and its secretion." (PMID 32370142, 2020). "Based on these observations, we can state that PROX1 and FGF2 remain in close relation also in thyroid cancer and regulate two signaling pathways, which cross each other." (PMID 31717665, 2019). "Interestingly, the treatment of CGTH-W-1 with FGF2 resulted in the higher expression of PROX1, which indicates mutual regulation of PROX1 and FGF2 signaling generating a regulatory loop in thyroid cancer cells." (PMID 31717665, 2019). "The difference in TIMP3 expression after PROX1 silencing in CGTH-W-1 and FTC-133 is probably a result of opposing regulation and variable baseline expression of MMPs and their inhibitors in cell lines derived from thyroid carcinomas." (PMID 31717665, 2019). "This, together with our data on the inversely correlated expression of PROX1 and MMP14 in the thyroid cancer biopsies, suggests that the increased invasiveness could be due to an increase in MMP14 expression." (PMID 29934628, 2018). "Then, using a number of cell lines from various thyroid cancer subtypes, we checked whether the negative correlation of PROX1 and FGF2 expression is a characteristic feature of FTCs or whether it occurs also in other thyroid cancers, such as PTCs and anaplastic cancer." (PMID 31717665, 2019). "We can assume that PROX1 functions as a transcription repressor for the FGF2 gene, but by itself is upregulated by FGF2 stimulation, thereby contributing to the negative feedback loop of FGF2 signaling in thyroid cancer cells." (PMID 31717665, 2019).
cholangiocarcinoma (6 papers, 2008 to 2025). A carcinoma that arises from the intrahepatic biliary tree (intrahepatic cholangiocarcinoma) or from the junction, or adjacent to the junction, of the right and left hepatic ducts (hilar cholangiocarcinoma). "Aim of the current study was to investigate the regulatory changes of Prox1-gene-expression in liver cirrhosis, in hepatocellular and cholangiocellular carcinomas." (PMID 18400094, 2008). "Our findings indicated that, apart from hepatocytes, Prox1-expression was also detectable in ductular cells within the fibrotic septa of cirrhotic livers and in the nuclei of intrahepatic cholangiocellular carcinoma cells." (PMID 18400094, 2008). "We have studied the expression of Prox1 in normal liver, liver cirrhosis and peritumoral liver samples in comparison to hepatocellular (HCC) and cholangiocellular carcinoma (CCC) at mRNA, protein and functional levels." (PMID 18400094, 2008). "To further explore the mechanisms of SOX1 in CCA, we detected the expression of two key proteins that interact with SOX1 (HES1, PROX1) and the signaling pathways related to cholangiocarcinoma (AKT, JNK, P38, ERK) by Western blot." (PMID 34876142, 2021).
esophageal squamous cell carcinoma (6 papers, 2014 to 2025). Esophageal squamous cell carcinoma (ESCC) is a type of esophageal carcinoma (EC) that can affect any part of the esophagus, but is usually located in the upper or middle third. "More specifically, PROX1 expression was found to be higher in esophageal squamous cell carcinoma (ESCC) tissues, compared to normal tissues." (PMID 35885529, 2022).
melanoma (6 papers, 2020 to 2025). A malignant, usually aggressive tumor composed of atypical, neoplastic melanocytes. "Feature heatmaps of melanoma (SOX10) and LEC (PROX1) markers showed that melanoma cells localized to 2 clusters (Melanoma I and II), and the remaining clusters (LEC I–VII) consisted of LECs and LECs*." (PMID 37971882, 2024). "Thus, tumors were induced by subcutaneous injection of B16/F10 cells, a murine melanoma cell line, on the back of Prox1+/– and WT littermate controls mice." (PMID 35663931, 2022). "Histological staining for Vegfr3 (Fig EV1B) and for the lymphatic markers Prox1 and Lyve1 confirmed the inhibitory effect of BO‐110 in tumor‐driven neolymphangiogenesis at the cutaneous melanomas or at distal organs (see lungs in Fig EV1C) of Vegfr3Luc‐GEMM mice." (PMID 34762341, 2021). "First, even though we have previously shown that Prox1+/– mice have a defective LV and lymphatic leakage, we do not directly evaluate lymph leakage in the DSS or melanoma models in this mouse model." (PMID 35663931, 2022).
oral squamous cell carcinoma (6 papers, 2014 to 2025). "Following this discovery, cultured oral squamous cell carcinoma cell lines reported increased levels of Prox1 in the “highly-metastatic” lines, which were found to activate VEGF-C expression." (PMID 33263009, 2020). "Likewise, circFNDC3B promotes vasculature formation and metastasis by sponging miR-181c-5p and upregulating SERPINE1 and PROX1 in oral squamous cell carcinoma." (PMID 41214390, 2025). "In the present study, we examined the expression of Prox1 and FOXC2 proteins in specimens from 163 cases with oral squamous cell carcinoma (OSCC)." (PMID 24647631, 2014). "Prospero homeobox 1 (PROX1) has been shown to function as a tumor suppressor gene or oncogene in various types of cancer, including oral squamous cell carcinoma (OSCC)." (PMID 25526434, 2014).
cervical carcinoma (5 papers, 2017 to 2022). A carcinoma arising from either the exocervical squamous epithelium or the endocervical glandular epithelium. "In HeLa-S3, the cervical carcinoma cell line (E117), PROX1 and NR2F6 were found by DeepHistone." (PMID 30967126, 2019). "Interestingly, PROX1 ITLVD and PROX1 and LYVE-1 PTLVD correlated significantly with the degree of stromal inflammation, indicating that inflammation may play a role in cervical cancer-associated lymphangiogenesis." (PMID 35885529, 2022). "Subsequently, the expression of REST, PROX1, and CHG-A in the non-neuroendocrine lung cancer cell lines H1299 and TKB5, the uterine cervical cancer cell line HeLa, and the neuroendocrine lung cancer cell line TKB16 was analysed by RT-PCR." (PMID 35094211, 2022). "However, the expression of PROX1 in the tumor cells did not correlate significantly with any of the clinicopathological parameters studied; therefore, this study could not support that PROX1 has any prognostic value in cervical cancer." (PMID 35885529, 2022).
follicular thyroid cancer (5 papers, 2017 to 2023). "Overall, these results indicate that loss of PROX1 in follicular thyroid cancer cells induces significant changes in the expression of genes involved in cellular focal adhesion, dynamic cytoskeleton transformation, determination of cell shape and migration." (PMID 31060342, 2019). "Our results suggest that hyperactivation of the PI3K/AKT signaling pathway resulting from PTEN inactivation due to an inactivating mutation may regulate Prox1 expression in follicular carcinoma-originating FTC-133 cells." (PMID 29371975, 2017). "The current study show that decrease of PROX1 expression suppress the malignant features of follicular thyroid cancer cells such as migration, motility and invasion." (PMID 31060342, 2019). "Follicular thyroid cancer-derived cells—CGTH-W-1—were transfected with PROX1-siRNA (small interfering RNA) and their proliferation, cell cycle, apoptosis and motility were then analysed." (PMID 31060342, 2019). "The aim of this study was to determine the molecular signature of PROX1 in follicular thyroid cancer and to perform functional analyses of the CGTH cells following PROX1 silencing." (PMID 31060342, 2019). "We had previously shown that PROX1 stimulates motility of follicular thyroid cancer cells and that its expression is correlated with the rates of both migration and invasion." (PMID 31060342, 2019). "CGTH cells, which were derived from a sternal metastasis of follicular thyroid carcinoma, express the highest levels of PROX1 among the three tested FTC-originating cell lines: FTC-133, CGTH-W1 and ML1." (PMID 31060342, 2019). "The PROX1 protein seems to contribute to follicular thyroid cancer metastases mainly by regulating cytoskeleton, focal adhesion and migration controlling pathways." (PMID 31060342, 2019). "Further studies should focus on the identification of cellular context-dependent signalling pathways regulated by PROX1 in follicular thyroid carcinoma." (PMID 31060342, 2019). "We observed that depleting PROX1 reduced migration, motility, invasive potential, and a capacity of anchorage-independent growth of these follicular thyroid cancer cells in vitro, while Prox1 overexpression in the same cell line had a contrary effect." (PMID 29371975, 2017). "Moreover, we determined the effect of Prox1 silencing and overexpression on the cellular processes associated with the metastatic potential of tumor cells: proliferation, migration, invasion, apoptosis and anchorage-independent growth, in the follicular thyroid carcinoma (FTC) FTC-133 cell line." (PMID 29371975, 2017). "All these results imply that Prox1 greatly promotes cell migration, motility and invasive potential in vitro, which suggests its involvement in the progression and spreading of follicular thyroid carcinoma cells." (PMID 29371975, 2017). "We reported previously levels of PROX1 mRNA in follicular thyroid carcinoma-derived cells as compared to cells derived from papillary thyroid cancer that may relate to follicular thyroid cancer progression and enhanced invasion." (PMID 31060342, 2019). "Finally, PROX1 expression was evaluated in human follicular thyroid cancer using RT-qPCR and Western blotting in the case of frozen specimens and immunohistochemistry for archived tissues." (PMID 31060342, 2019). "Although ITGA2 has been shown to be a target gene for certain microRNAs in aggressive papillary thyroid carcinoma, the impact and significance of its increased expression in follicular thyroid carcinoma cells upon PROX1 silencing, like that of the ITGA11 downregulation, remains to be clarified." (PMID 31060342, 2019). "In conclusion, our data strongly support a hypothesis that PROX1 may play an important role in tumorigenesis and progression of follicular thyroid carcinoma." (PMID 29371975, 2017).
follicular thyroid cancer (continued). "Given that Prox1 expression and function depend on the tissue and cell context, further studies should focus on identifying genes whose products regulate PROX1 expression in follicular thyroid cancer in order to elucidate the precise function of this protein in FTC development and progression." (PMID 29371975, 2017). "However, it is unclear whether and how the PROX1 gene is involved in thyroid follicular cancer (FTC) tumorigenesis." (PMID 29371975, 2017). "Comparably, in follicular thyroid cancer (FTC), the overexpression of Prospero homeobox 1 (PROX1), a key regulator of lymphangiogenesis, resulted in a decrease in several FGF signaling pathway members, including the downregulation of bFGF." (PMID 37048074, 2023). "We examined the effect of PROX1 on the motility of the follicular thyroid carcinoma-derived CGTH cells by analysing their migratory and invasive potential, following the PROX1 knock-down." (PMID 31060342, 2019). "Herein, we studied the role of PROX1 in angiogenesis in cell lines derived from follicular thyroid cancer (FTC: FTC-133) and squamous cell carcinoma of the thyroid gland (SCT: CGTH-W-1) upon PROX1 knockdown." (PMID 31717665, 2019). "In conclusion, we have shown that Prox1 plays an important role in the development of FTC and that its suppression prevents, whereas its overexpression promotes, the malignant behavior of thyroid follicular cancer cells." (PMID 29371975, 2017). "We chose the CGTH-W-1 cell line, derived from a sternal metastasis of follicular thyroid carcinoma, because it expresses the highest PROX1 levels among the three previously tested cell lines: FTC-133, ML-1 and CGTH-W-1 (PROX1 expression in CGHT cells is about 2-fold higher than in FTC-133 cells)." (PMID 31060342, 2019). "This suggests that Prox1 activity is rather not dependent on the genetic background determining the regulation of these processes in follicular thyroid cancer cells." (PMID 29371975, 2017). "Of note, we did not observe changes in the expression of proteins from the ERK1/2 pathway in response to depletion or overexpression of Prox1, which suggests that PROX1 is not involved in the regulation of this pathway in follicular thyroid cancer (data not shown)." (PMID 29371975, 2017). "Our results for follicular thyroid cancer cells, FTC-133, show that modifying Prox1 expression does not influence follicular cell cycle, apoptosis or proliferation." (PMID 29371975, 2017).
kaposiform hemangioendothelioma (5 papers, 2014 to 2025). Kaposiform hemangioendothelioma is a very rare, aggressive, vascular tumor manifesting in the neonatal period or in infancy as cutaneous vascular tumors to large infiltrative lesions. "Along with other vascular tumors, kaposiform hemangioendothelioma (KHE) has shown ectopic overexpression of the human Prox1 gene, a nuclear transcription factor associated with the lymphatic endothelium." (PMID 41303262, 2025). "A study of Kaposiform hemangioendothelioma revealed that overexpression of PROX1 facilitates a more aggressive behavior through induction of genes involved in cell adhesion, proteolysis, and migration, thereby enhancing cell invasion and migration into the surrounding tissue." (PMID 32370142, 2020).
liver cancer (5 papers, 2022 to 2025). An epithelial or non-epithelial malignant neoplasm that arises from the liver. "This demonstrates that PROX1 functions as a tumor suppressor by impeding tumor initiation and progression in distinct liver cancer mouse models." (PMID 39948437, 2025). "We found decreased PROX1 expression in patients with liver cancer, which supports the role of cell fate plasticity in disease." (PMID 39948437, 2025). "In mice, Prox1 OE reduced neoplastic transformation and progression across three liver cancer models." (PMID 39948437, 2025). "This shows that PROX1 primarily closes chromatin in liver cancer cells and reduces their proliferation by gene repression." (PMID 39948437, 2025). "In particular, Prox1 expression has been correlated with tumorigenesis in colon, gastric, prostate, and liver cancers." (PMID 37508533, 2023). "In liver cancer, PROX1 can also enhance the stability of p65 by binding USP7 to affect angiogenesis in liver cancer cells." (PMID 35875077, 2022). "In liver cancer, PROX1 can increase the stability of the transcription factor hypoxia-inducible factor 1α (HIF1α) by recruiting histone deacetylase (HDAC1), leading to EMT of liver cancer cells." (PMID 35342346, 2022). "In line with PROX1 expression differences in samples of patients with human liver cancer, manipulating PROX1 in mouse liver cancer models could switch the transformation trajectory of hepatocytes between CCA and HCC." (PMID 39948437, 2025). "Intriguingly, the CCA marker KRT19 and the PROX1 targets PRRX1 and PPARG exhibited a negative correlation with PROX1 expression in tumor tissue, suggesting that PROX1 could regulate liver cancer plasticity and HCC versus CCA fate." (PMID 39948437, 2025). "Indeed, the PROX1 protein abundance was reduced in response to glucose deficiency, metformin or MK8722 (a selective on-target synthetic AMPK activator) treatment in liver cancer cells and mouse embryonic fibroblasts (MEFs)." (PMID 36433955, 2022). "To link the role of PROX1 to its phosphorylation by AMPK, we next determined whether the S79E mutant of PROX1 also rendered a disadvantage in tumour growth in the DEN-induced liver cancer mouse model." (PMID 36433955, 2022).
lymph node metastasis (5 papers, 2014 to 2024). "Vascular endothelial growth factor C (VEGF-C), interleukin-4 (IL-4), colony-stimulating factor 2 (CSF2), prospero homeobox 1 (PROX1), and TEK receptor Tyrosine Kinase (TEK) is significantly associated with lymph node metastasis in renal cell carcinoma (RCC)." (PMID 38167072, 2024). "Patients with lymph node metastasis and triple negative subtype acquired the highest expression of PROX1." (PMID 35342346, 2022). "A total of 1210 GC patients from 6 studies reported the relationship between lymph node metastasis (N1-3 and N0) and the expression of PROX1 (OR: 2.161, 95% CI 0.808–5.779, P = 0.125)." (PMID 35346069, 2022). "In addition, the PROX1 immunostaining levels were positively correlated with tumor nuclear grade and lymph node metastasis." (PMID 24797520, 2014). "The expression of PROX1 was shown to lack a significant relationship to gender, TNM stage, depth of invasion, tumor size, stage, distant metastasis, or lymph node metastasis in statistically." (PMID 35346069, 2022). "Meta-analysis showed that PROX1 expression was not related to lymph node metastasis in statistic." (PMID 35346069, 2022). "We observed significantly higher PROX1 and α-SMA expression in patients of CRC with lymphatic invasion or lymph node metastasis compared with those of CRC without lymphatic invasion and lymph node metastasis." (PMID 38244581, 2024). "The results confirmed significantly higher PROX1 and α-SMA gene expression in patients with CRC with lymphatic invasion or lymph node metastasis compared with those without." (PMID 38244581, 2024). "We found PROX1 expression is not correlated with gender, TNM stage, depth of invasion, tumor size, stage, distant metastasis and lymph node metastasis." (PMID 35346069, 2022). "In our meta-analysis, PROX1 expression is not related to gender, TNM stage, depth of invasion, tumor size, stage, tumor metastasis or lymph node metastasis in GC." (PMID 35346069, 2022).